AKR1C1 (aldo-keto reductase family 1 member C1)
Diseases named in the same sentence as AKR1C1 in open-access papers (continued):
Sharing a sentence is not in itself a finding about the gene and the disease.
prostate carcinoma (15 papers, 2010 to 2025). A carcinoma that arises from epithelial cells of the prostate gland. "This obvious growth constraint and cell cycle arrest induced in prostate cancer by adiols caused us to confirm the functional expression of the enzymes they originate from, especially AKR1C1 and AKR1C2." (PMID 29682196, 2018). "AKR1C1 has a role in controlling plasma progesterone levels in pregnancy while AKR1C2 has been linked to prostate cancer." (PMID 21217827, 2010). "To determine the magnitude of degradation of target proteins resulting from exposure to our small molecule inhibitor scaffold, we investigated the ability of inhibitor 3 and warhead 4 to degrade AKR1C3, AKR1C1/2, and ARv7 in 22Rv1 prostate cancer cells." (PMID 38684887, 2024). "Several studies suggest a critical role for the canonical function of AKR1C1 in the aggressiveness of hormone-related cancers, which is especially interesting in case of prostate cancer." (PMID 31447885, 2019). "AKR1C1, a member of the aldo-keto reductase family, has been reported to be highly expressed in various types of cancer, such as small cell lung cancer, endometrial cancer, prostate cancer." (PMID 34702254, 2021). "Specific inhibitors of AKR1C1 (3-bromo-5-phenylsalicylic acid) and AKR1C3 (tolfenamic acid, indomethacin; phase I/II trial in prostate cancer, NCT02935205)) are also available." (PMID 39272833, 2024). "AKR1C1 and AKR1C3 have both been shown to be greatly increased in bone marrow metastases when compared to prostate cancer primary tumor sites." (PMID 37484909, 2023). "AKR1C3, comes from the same family as AKR1C1, has not been proved to have similar functions as AKR1C1 in bladder cancer, but it is often overexpressed in prostate cancer tissues and cell lines." (PMID 38978149, 2024). "Among them, AKR1C1 and AKR1C3 have been reported to be upregulated in human tumors and identified as prognostic markers for various forms of cancer, including breast, colon, bladder, and prostate cancers." (PMID 34830394, 2021). "In addition, it is known that the androgen biosynthesis enzymes AKR1C1, AKR1C2, and AKR1C3 are upregulated in prostate cancer." (PMID 29682196, 2018). "The expression of aldo-keto reductase (AKR) family genes, including those for AKR1C1 and AKR1C2, which contribute to the detoxification of lipid peroxidation products, was recently shown to be markedly increased in an established erastin-resistant clone of DU-145 human prostate cancer cells." (PMID 30333913, 2018). "The vitamin K-2/SXR mechanism was proven to activate expression of AKR1C1 and AKR1C2 in osteoblastic cells, but TERE1/K-2-mediated activation of SXR has not been previously studied in prostate cancer." (PMID 23919967, 2013).
bladder cancer (10 papers, 2016 to 2024). "In this study, we obtained the critical gene AKR1C1 that causes resistance of bladder cancer to THP via CRISPR/dCas9 SAM." (PMID 37173953, 2023). "The results confirmed that high levels of AKR1C1 could inhibit the ability of THP to induce apoptosis in bladder cancer cells, thus causing bladder cancer cells to be resistant to THP." (PMID 37173953, 2023). "Overexpression of AKR1C1 could promote bladder cancer cell lines to resist THP-induced apoptosis, while inhibition of AKR1C1 could make bladder cancer cells more susceptible to THP treatment and apoptosis." (PMID 37173953, 2023). "AKR1C1 was proved to be related with the invasive potential and drug resistance of metastatic bladder cancer cells." (PMID 38978149, 2024). "Then, the original expression level of AKR1C1 was changed in the different bladder cancer cell lines by overexpression of the lentivirus plasmid, interfering with siRNA or using inhibitors." (PMID 37173953, 2023). "AKR1C1 has been reported to be significantly overexpressed in the metastatic tissues of bladder cancer." (PMID 37173953, 2023). "This study not only verified that AKR1C1 can cause resistance of bladder cancer cells to THP both in in vivo and in vitro, but also found that THP treatment can gradually increase the expression of AKR1C1, thus causing resistance to the drug." (PMID 37173953, 2023). "Through the study of tissue microarray and IHC methods, AKR1C1 was found to be significantly higher in the bladder cancer tissues than in adjacent tissues, which indicated that AKR1C1 was originally high in the bladder cancer tissues at the protein level." (PMID 37173953, 2023). "AKR1C1 expression in the cancer tissue was significantly higher than that in the normal tissue surrounding cancer and was significantly higher in the Ta/T1 bladder cancer tissue than that at the T2/T3 stage." (PMID 37173953, 2023). "The effects of AKR1C1 on the proliferation and colony formation on the bladder cancer cells were tested." (PMID 37173953, 2023). "Previous studies focusing on their potential role in cancer biology, demonstrated a close relationship between AKR1C1 and sex hormone-related ovarian and bladder cancers." (PMID 37189628, 2023). "In clinical tissues, the AKR1C1 content in the bladder cancer tissues was significantly higher than that that in the normal adjacent tissues, while it was higher in the Ta/T1 tissues than in the T2/T3 tissues." (PMID 37173953, 2023). "Other factors are implicated in Rac1-mediated EMT, such as the metabolic enzyme AKR1C1 (aldo-keto reductase 1C1), which mediates the invasive potential and drug resistance of metastatic bladder cancer cells." (PMID 35740379, 2022). "The inhibition of AKR1C1 reduces the invasion/metastatic potential of bladder cancer cells via the regulation of the Rac1/Src/Akt pathway and modulation of the production of inflammatory cytokines, such as interleukin 1β (IL-1β)." (PMID 35740379, 2022). "By microarray analysis, AKR1C1 was found to be up-regulated in metastatic lesions, which was verified in metastatic human bladder cancer specimens." (PMID 27698389, 2016). "In this study, immunohistochemistry demonstrated that AKR1C1 was highly expressed in metastatic lesions of human bladder cancer patients." (PMID 27698389, 2016). "The significance of this IL-1β dependent increase in AKR1C1 was confirmed in clinical specimens of human bladder cancer tissues." (PMID 27698389, 2016). "To examine the role for AKR1C1 in bladder cancer metastasis, we eliminated AKR1C1 in the UM-UC-3 cells using a siRNA technique." (PMID 27698389, 2016). "An inflammatory cytokine, interleukin-1β, was found to increase AKR1C1 in bladder cancer cell lines." (PMID 27698389, 2016). "Increased AKR1C1/2/3 levels are observed in cisplatin-resistant bladder cancer and colon cancer cell lines, leukemia cells continuously treated with daunorubicin, and in cisplatin-resistant ovarian cancers." (PMID 26799320, 2016).
bladder cancer (continued). "To ensure clinical significance, we examined the AKR1C1 levels using surgically resected specimens derived from bladder cancer patients, including 33 primary and 5 metastatic lesions involving the lymph nodes (n = 3), lungs (n = 1), and liver (n = 1)." (PMID 27698389, 2016). "IL-1β enhanced the expression of AKR1C1 in the three bladder cancer cell lines, UM-UC-3, TCC-SUP, and 5637 cells." (PMID 27698389, 2016). "Therefore, compared with normal adjacent tissues, the high level of AKR1C1 in bladder cancer tissues was more capable of eliminating the anticancer activity of multiple drugs and gained certain advantages for the chemotherapy resistance of bladder cancer." (PMID 37173953, 2023). "Overexpression of AKR1C1 could increase the resistance of T24 bladder cancer cell lines to THP, while interference or inhibition of AKR1C1 could increase the sensitivity of RT4 bladder cancer cell lines to THP." (PMID 37173953, 2023). "The AKR1C1 gene determined through positive screening of the CRISPR/dCas9 SAM library could promote the human T24 bladder cancer cell line to develop resistance to THP in vivo and in vitro." (PMID 37173953, 2023). "In addition, the AKR1C1 content in the Ta/T1 bladder cancer tissue was higher than those in the T2/T3 patients." (PMID 37173953, 2023). "AKR1C1 inhibitor could enhance the ability of THP to induce apoptosis in bladder cancer cells, improve the anticancer ability of THP, promote tumor cell apoptosis, and reduce drug resistance of tumor cells." (PMID 37173953, 2023). "After receiving THP treatment, the bladder cancer cell lines could upregulate the expression of the AKR1C1 gene through the ROS/KEAP1/NRF2 pathway, leading to resistance to THP treatment." (PMID 37173953, 2023). "Finally, the expression level of AKR1C1 was measured in the bladder cancer tissues of eight clinical patients from the center at the time of initial onset and recurrence." (PMID 37173953, 2023). "Interference with AKR1C1 gene expression or the use of AKR1C1 inhibitor could significantly increase the sensitivity of the human RT4 bladder cancer cell line to THP and reduce drug resistance." (PMID 37173953, 2023). "Moreover, AKR1C1 mRNA levels in recurrent bladder cancer tissues treated with pirarubicin were higher than those in the NMIBC tissues initially found." (PMID 37173953, 2023). "Overexpression of AKR1C1 could inhibit THP-induced apoptosis of bladder cancer cells by inhibiting the production of 4-HNE and intracellular ROS." (PMID 37173953, 2023). "Results showed that the high expression of AKR1C1 could enhance the drug resistance of bladder cancer to THP both in vivo and in vitro." (PMID 37173953, 2023). "The effect and mechanism of AKR1C1 on THP resistance in bladder cancer were explored using cell biology, molecular biology, and pharmacology and combined with AKR1C1 inhibitor (aspirin) and ROS inhibitor (scavenger) to rescue drug-resistant bladder cancer cells to recover their sensitivity to THP." (PMID 37173953, 2023). "Therefore, AKR1C1 contributes to the development of chemoresistance and induction of stemness-like features in metastatic bladder cancer." (PMID 27698389, 2016). "Although AKR1C1 is reported to be involved in tumour metastasis through interaction with STAT3 in NSCLC27 and to promote invasion of bladder cancer cells, evidence supporting the facilitation of metastasis is still lacking." (PMID 32307891, 2020). "The molecular machinery for the AKR1C1-dependent up-regulation of EMT and invasiveness was examined with AKR1C1 knockdown bladder cancer cells that exhibited less in vitro invasiveness." (PMID 27698389, 2016). "For verification, the cytokine effects on other bladder cancer cell lines, such as TCC-SUP and 5637, were examined, and IL-1β increased the AKR1C1 levels in both cell lines." (PMID 27698389, 2016).
bladder cancer (continued). "Among the eight patients with recurrent bladder cancer, in one patient, the expression of AKR1C1 in the tumor tissue at the time of recurrence was not significantly different from that at the time of initial onset." (PMID 37173953, 2023). "Though further investigations are needed, these studies support the possibility of using TSPAN7, AKR1C1/2, and CYR61 as biomarkers for resistance and that knockdown or inhibition of these genes may prevent or reduce platinum chemoresistance in bladder cancer." (PMID 26799320, 2016). "However, in primary bladder cancer, the drug resistance mechanism of AKR1C1 and THP has not yet been elucidated." (PMID 37173953, 2023). "However, the expression level of AKR1C1 would not change the proliferation, invasion, or migration of bladder cancers." (PMID 37173953, 2023). "However, the expression level of AKR1C1 would not affect the proliferation, invasion, or migration of bladder cancer cells." (PMID 37173953, 2023). "However, AKR1C1 did not affect the proliferation, invasion, or migration of the bladder cancer cells." (PMID 37173953, 2023).
colon cancer (10 papers, 2014 to 2025). "It was noted that reduction of AKR1C1 by siRNA in human colon cancer enhances the sensitivity toward cisplatin, whereas overexpression of AKR1C1 is highly associated with the cisplatin resistance." (PMID 26824415, 2016). "For example, upregulated AKR1C1 results in ferroptotic resistance in melanoma and small cell lung carcinoma, and AKR1C1 inhibitors potentiate ferroptosis in colon cancer." (PMID 39478199, 2025). "The overexpression of AKR1C1 involved in the resistance of cis-diamminedichloroplatinum (CDDP) in colon cancers." (PMID 34046350, 2021). "In the study of colon cancer, specific inhibitors of AKR1C1 and AKR1C3 or knockdowns of the genes in the resistant cells were used to resensitize the cells to cisplatin toxicity." (PMID 34830394, 2021). "AKR1C3 is an aldo–keto reductase that has been described as responsible for gaining resistance against cisplatin treatment when overexpressed in colon cancer cells together with AKR1C1[Gene ID: 1645]." (PMID 26359356, 2015). "Besides, AKR1C1 inhibitors could be a therapy medicine to sensitive ferroptosis in colon cancer." (PMID 34046350, 2021). "We also performed immunohistochemistry against AKR1C1 and CARS1 in the colon cancer tissues and adjacent tissues." (PMID 34046350, 2021). "Immunohistochemistry was used to detect expression of AKR1C1 and CARS1 in colon cancer tissues and adjacent tissues." (PMID 34046350, 2021). "In colon cancers, studies reported that the up-regulated expression of AKR1B10, AKR1C1, AKR1C2 and AKR1C3 contributed to chemotherapeutic drug resistance indirectly, by reducing oxidative stress generated by these chemotherapeutic agents." (PMID 27635343, 2016). "In melanoma, upregulated AKR1C1 resulted in ferroptotic cell death resistance, which perhaps could explain the CDDP resistance in colon cancer and pointed out a possible strategy to overcome CDDP resistance in CC." (PMID 34046350, 2021). "The resistance towards the chemotherapeutic drug cisplatin in colon cancers is believed to be a result of decreased sensitivity toward cellular damages evoked by oxidative stress-derived aldehydes, 4-hydroxy-2-nonenal and 4-oxo-2-nonenal, that are detoxified by AKR1C1 and AKR1C3." (PMID 25243088, 2014). "In the HPA database, we found that the expression of AKR1C1, ALOX12, and CARS1 in colon cancer tissue is higher than normal tissue and the expression of FDFT1 in colon cancer tissue is lower than normal tissue by immunohistochemistry, which is consistent with our results." (PMID 34046350, 2021).
ovarian carcinoma (10 papers, 2013 to 2025). A malignant neoplasm originating from the surface ovarian epithelium. "Altered expression of AKR1C1 has been involved in many diseases, For example, a clear association between increased expression of AKR1C1 and the development of cisplatin-resistance in human ovarian carcinoma cells was observed." (PMID 24003325, 2013). "AKR1B10 has been shown to increase FAO in metastatic breast cancer, and the inhibition of AKR1C1/2 can sensitize platinum‐resistant ovarian cancer toward carboplatin." (PMID 39924751, 2025). "We show that an inhibition of this pathway either by NFE2L2 silencing or direct AKR1C1/2 inhibition by MPA resensitizes ovarian cancer cells to CTX and results in reduced viability, proliferation, and an increased apoptosis rate." (PMID 35115586, 2022). "We first determined the basal expression of NRF2 and AKR1C1/2 in a panel of well-established ovarian cancer cell lines." (PMID 35115586, 2022). "All ovarian cancer cell lines tested had substantially higher NRF2 and AKR1C1/2 mRNA and protein levels than the benign ovarian epithelial cell line HOSEpiC." (PMID 35115586, 2022). "Ovarian cancer cells (2008, SKOV3 and A2780) show an increased platinum resistance by AKR1C1/2 overexpression." (PMID 35115586, 2022). "It was discovered that upregulated mRNA of the AKR1C1–4 enzymes (originally known as dihydrodiol dehydrogenases) and AKR1A1 induces a resistance to cisplatin in human ovarian cancer cells." (PMID 35159076, 2022). "In this study, we investigate AKR1C1/2, target of NRF2, in a well-established EOC collective by immunohistochemistry and in a panel of ovarian cancer cell lines including platinum-resistant clones." (PMID 35115586, 2022).
endometrial cancer (9 papers, 2016 to 2025). Primary or metastatic malignant neoplasm involving the endometrium (mucous membrane that lines the endometrial cavity). "Inversely, silencing of Nrf2 or AKR1C1 rendered endometrial cancer cells more susceptible to progestin treatment." (PMID 26824415, 2016). "Increased AKR1C1 expression might be associated with the pathological progression of endometrial cancer." (PMID 39519053, 2024). "However, while maintaining a high level of Nrf2 in Nrf2 stably-expressed endometrial cancer cells, silencing of AKR1C1 alone abolished Nrf2-associated progestin resistance." (PMID 26824415, 2016). "Recently, it was also found that brusatol sensitized endometrial cancer to progestin by suppressing NRF2-TET1 AKR1C1-mediated progestin metabolism." (PMID 39519053, 2024). "Suppression of AKR1C1 by brusatol resulted in decreased progesterone catabolism and maintained potent progesterone to inhibit endometrial cancer growth." (PMID 39519053, 2024). "This is consistent with what we observed in our previous and current studies that the level of Nrf2/AKR1C1 is persistently decreased, while PR is elevated in endometrial cancer cells after MPA withdrawal." (PMID 26824415, 2016). "As a unique inhibitor of Nrf2 expression, brusatol was examined and has been found to be able to reverse progestin resistance in the endometrial cancer cell lines with decrease of Nrf2/AKR1C1." (PMID 26824415, 2016). "Based on these findings, we think that the elevated AKR1C1 and Nrf2 in endometrial cancer may represent a poor prognosis due to the emergence of progestin resistance." (PMID 26824415, 2016). "Down regulation of Nrf2/AKR1C1 is benefit to endometrial cancer cells sensitizing to progestin." (PMID 26824415, 2016). "The aberrant expression of AKR1C1 has been observed in endometrial cancers, and overexpression of AKR1C1 may result in an inhibition of cellular production of progestin receptor." (PMID 26824415, 2016). "Based on this study and our study on endometrial cancer, we recommend follow-up of interactions between acrylamide intake and SNPs for ovarian and endometrial cancer risk, particularly SNPs in CYP2E1, GSTs, the HSD3B1/B2 gene cluster, AKR1C1, NQO1, GPX1 and MGC12965." (PMID 28391539, 2017). "In the study of endometrial cancer (EC), we found that Brusatol sensitizes the cancer to progestins by inhibiting the NRF2-TET1-AKR1C1 pathway, which reduces AKR1C1 expression and decreases progesterone metabolism." (PMID 40258841, 2025). "Along the line of searching for biomarkers of prediction and revealing the molecular mechanism of progestin resistance, we recently came across the findings that Nrf2 and AKR1C1 were overexpressed only in partially responding and non-responding endometrial cancer samples after progestin treatment." (PMID 26824415, 2016). "After observing such a striking Nrf2 and AKR1C1 expression pattern in partial and non-responding endometrial samples, we sought to investigate if these two molecules may contribute to progestin resistance in endometrial cancer." (PMID 26824415, 2016).
gastric cancer (8 papers, 2019 to 2025). A primary or metastatic malignant neoplasm involving the stomach. "The aldo keto-reductase 1 family genes (AKR1C1-3) encode steroidogenic genes which, although expressed at high levels in some cancers, are also downregulated in others such as breast and gastric cancers." (PMID 32537432, 2020). "In acquired cisplatin-resistance and metastatic ovarian and gastric cancer cells, AKR1C1 is upregulated by IL-6 stimulation and nuclear factor erythroid 2-related factor 2 (Nrf2) and promotes chemoresistance." (PMID 31182137, 2019). "Moreover, the involvement of upregulated AKR1C1 and 1C3 in oxaliplatin-resistant gastric cancer cells has been reported." (PMID 34830394, 2021).